CTLA4 (cytotoxic T-lymphocyte associated protein 4)
Diseases named in the same sentence as CTLA4 in open-access papers (continued):
Sharing a sentence is not in itself a finding about the gene and the disease.
tumor (continued). "It has been unraveled that the tumor microenvironment (TME) contains macrophages skewed toward the tumor-promoting type (TAM) and T-cells, with the latter being potential targets for, e.g., Nivolumab and Ipilimumab antibody therapy targeting the T-cell immune checkpoints PD-1 and CTLA4." (PMID 40002275, 2025). "One strategy to leverage the anti-tumor activity of CTLs involves activating pre-existing, endogenous tumor-directed CTL clones by administering immune checkpoint inhibitors or mAbs that block receptors such as PD-1 and CTLA-4 which are involved in T-cell-inhibitory pathways." (PMID 39997328, 2025). "Additionally, blocking sialylation with pharmacological agents like ambroxol sensitizes the tumor to immune checkpoint blockade (ICB) therapies, such as anti-PD-1 and anti-CTLA4, significantly improving tumor control and extending survival in preclinical models." (PMID 40330466, 2025). "The success of immune checkpoint blockade (ICB) therapies, such as antibodies targeting PD-1, PD-L1, and CTLA-4, is critically dependent on the presence of a pre-existing T-cell infiltrate within the tumor, as tumors lacking this infiltrate are typically resistant to ICB." (PMID 41516196, 2025). "The reasoning behind combining CTLA-4 with PD-1/PD-L1 blockade lies in their complementary mechanisms of action: inhibition of CTLA-4 increases T-cell expansion during the initial immune priming phase, while PD-1/PD-L1 blockade re-invigorates effector T cells within the tumor microenvironment (TME)." (PMID 40561796, 2025). "The down-regulation of immune-checkpoint receptors (PD1, CTLA4, TIGIT, etc.), up-regulation of cytokines (IFN-γ, TNF-α, IL2), and activation of granzyme and perforin, etc., remained the primary readouts to characterize the antitumor potential of tumor-infiltrated and activated T-cells." (PMID 40593750, 2025). "Positive PD-L1 expression on the tumor surface serves as an indicator that a patient may be responsive to PD-1-PD-L1-targeting drugs, with CTLA-4 presence on T cells serving as a marker that a patient may be responsive to anti-CTLA-4 immunotherapeutic drugs." (PMID 40429725, 2025). "Tumor-infiltrating T-cells isolated from both biopsy and CUSA tissue fragment materials were divided into helper (CD4+) and cytotoxic (CD8+) T-cells showing similar expression levels of PD-1, CTLA-4, and TIM-3 checkpoint receptors between biopsy and CUSA tissue fragments." (PMID 40980437, 2025). "However, additional combination of MUC1 LCP-mRNA with an anti-CTLA4 antibody was needed to enhance CD8+ T cell recruitment, inhibit the tumor-promoting STAT3 pathway, and further enhance anti-tumor responses in the murine triple negative breast cancer cells, in vivo." (PMID 41012179, 2025). "The results showed that there was no significant reduction in tumor growth compared to the control group, suggesting that butyrate may inhibit the anti-tumor efficacy of CTLA-4 in mice." (PMID 40066456, 2025). "Notably, MARCO blockade synergizes with anti-CTLA-4 therapy, but not anti-PD-1, to significantly improve tumor control and survival in murine tumor models." (PMID 41002423, 2025). "Building on the approval of combined CTLA-4 and PD-L1 inhibitors plus chemotherapy in advanced disease, ipilimumab was tested concurrently with cCRT, followed by nivolumab (NCT03663166, phase 1|2, n=19), for patients with large tumor volume (median planning target volume 627.9 cc)." (PMID 41415542, 2025). "However, without concurrent CTLA-4 inhibition—which enhances T-cell priming and expansion—the immune activation from monotherapy appears inadequate for long-term tumor control." (PMID 41011180, 2025). "For instance, combining CTLA‐4 inhibitors with PD‐1/PD‐L1 antibodies can activate the INF‐γ pathway and other pathways, potentially inducing the upregulation of additional immune checkpoints on tumor‐infiltrating lymphocytes, ultimately resulting in treatment failure." (PMID 40672434, 2025).
tumor (continued). "Given the similar risk of recurrence, this suggests that patients with node-negative basal-like BC and a high tumor CTLA4 expression may safely forego adjuvant chemotherapy." (PMID 40523912, 2025). "Similarly, combining CTLA-4 phosphorylation modulators with CTLA-4-based therapies could restore T cell function, amplifying the overall anti-tumor immune response." (PMID 40040703, 2025). "The negative impact of CTLA-4 expression in the TME has been explored in canine tumor models." (PMID 40463388, 2025). "Even for well-studied axes, translation can bifurcate: butyrate may potentiate PD-1 therapy yet limit CTLA-4 efficacy; TMAO shows tumor-promoting programs in some contexts but improves ICB response in others, and can be depleted by broad-spectrum antibiotics that also impair CAR-T potency." (PMID 41339918, 2025). "The favorable safety profile observed in this case aligns with the design rationale of cadonilimab, which aims to reduce peripheral toxicity mediated by CTLA-4 targeting through its unique structure (lacking Fc effector function and enriched in the tumor microenvironment)." (PMID 41561746, 2025). "NANPs designed to deliver siRNAs against cancer immunity-inhibitory machinery – e.g., PD-1 and CTLA4 on T-cells, PD-L1 on cancer cells and APCs, VEGF on tumor vasculature, LAG, TIM3, HLA-G, TGFβ on tumor cells – may aid in overcoming barriers created by four steps of the cancer immunity cycle: III." (PMID 40831543, 2025). "In a previous small cohort, the investigators found that CTLA-4 expression was absent in MB tumours in the cohort, possibly because the absence may reflect the limited sample size." (PMID 41285059, 2025). "While anti-tumor T cell subsets, such as T_C1_Cytotoxic cells, were enriched in the low-PCD group, the high-PCD group exhibited a significant accumulation of exhausted T cells, characterized by the expression of exhaustion markers such as LAG3, HAVCR2, CTLA4, TIGIT, and CXCL13." (PMID 40740783, 2025). "Remarkably, the initial clinical trials, and now the routine clinical application, of PD-1 and CTLA-4 immune checkpoint therapies for ccRCC treatment were never based on clear pre-clinical evidence that was directly related to this tumour entity, due to the absence of appropriate mouse models." (PMID 40473819, 2025). "It is possible that with a combination approach, anti-tumor immune responses are further enhanced by non-redundant targeting of the PD-1/PD-L1 and CTLA-4 signaling axes, or by specific tumor mutational features that benefit from CTLA-4 inhibition." (PMID 38430375, 2024). "Consequently, our study seeks to evaluate the impact of anti-CTLA4/NKG2A aptamers on immune checkpoint interactions, specifically examining CTLA4-CD80/CD86 and NKG2A-HLA-E interactions between CD8 T cells/NK cells and tumor cells." (PMID 38473398, 2024). "Interestingly, CTLA-4 blockade increased the RT-induced Treg response in both TdLNs and non-TdLNs, and the Treg population remained high in the tumor." (PMID 38349740, 2024). "Our data also suggested that anti-CTLA-4 Ab treatment led to Th1 accumulation in tumors, and IFN-g produced by these cells could induce cell cycle arrest and apoptosis in tumor cells, thereby possibly leading to tumor elimination." (PMID 39106430, 2024). "One such factor is the interaction of PD-1, CTLA-4, and TIM-3 inhibitory receptors on the T-cell surface with ligands on the surface of the cancer cell, which sends an inhibitory signal to the T-cell to halt its anti-tumor activity, rendering it ineffective against the tumor." (PMID 39343796, 2024). "Interestingly, the combination of anti-CTLA-4 with RMC-4998 and RMC-4550 displayed a similar effect to the triple combination with anti-PD-1, whereas the quadruple combination of targeted and ICB therapies led to tumour eradication in almost all mice." (PMID 39322643, 2024).
tumor (continued). "Furthermore, high-dose AA has been shown to modulate the infiltration of immune cells into the tumor microenvironment, enhance the cytotoxic activity of adoptively transferred CD8 + T cells, and cooperate with anti-PD1 and anti-CTLA-4 treatments in mice with syngeneic tumors." (PMID 39896806, 2024). "Furthermore, we observed significant reduction of anti-CTLA4 treatment efficacy by ABx only in the primary tumor but not in the abscopal tumor." (PMID 38500667, 2024). "In mice, localized administration of CD47nb increased the activation of tumor-infiltrating T cells while dramatically inhibiting tumor development In the follow-up study, E. coli Nissle 1917 was engineered with SLC in a subsequent effort to generate nanobodies targeting PD-L1 and CTLA-4." (PMID 39594765, 2024). "By targeting immunosuppressive molecules such as PD-1/PD-L1, CTLA-4, TIM-3, and NKG2A, or combining them with tumor-specific antigens, they can activate immune cells and enable them to effectively target the TME, resulting in specific tumor cell-killing effects." (PMID 39456702, 2024). "In cancer, CTLA4 is harnessed by cancer cells to hinder the antitumor immune response through manipulation of the expression of CTLA4 ligands (CD80 and CD86) on APCs within the tumor microenvironment, enabling CTLA4 on regulatory T cells (Tregs) to suppress cytotoxic T cell activity." (PMID 39409893, 2024). "Exosomes prepared from ovalbumin (OVA)‐pulsed, activated DC were modified with anti‐CTLA‐4 antibody (EXO–OVA–mAb), which increased the migration of CD4 and CD8 T cells to the tumor site and increased the ratio of CTLs/Tregs in the microenvironment of the B16 melanoma tumor model." (PMID 39015555, 2024). "Autopsy specimens from two patients with melanoma who died from myocarditis after receiving combination therapy with CTLA-4/PD-1 antibodies revealed shared T cell clones in the tumor, heart, and skeletal muscle, without any evidence of adjacent tissue involvement, including the smooth muscle." (PMID 38226621, 2024). "Therefore, blocking their inhibitory signaling using anti-PD1/CTLA-4 antibodies could rejuvenate exhausted CD8+ T cells, enhance their cytotoxicity, promote tumor cell lysis, and restrict tumor metastasis." (PMID 38291496, 2024). "Furthermore, an analysis utilizing the TSIDB database uncovered a significant correlation between AEG-1 and several key factors, including the tumor-promoting cell Th2, immune activator IL6, CXCR4, immunosuppressants CTLA4, IL1, IDO1, LAG3, PDCD1, TGFB1, and the DHC molecule HLA-DPA1." (PMID 39483471, 2024). "Additionally, anti–PD-1 and anti–CTLA-4 ICIs are known to have distinct mechanisms of action, with anti–CTLA-4 agents more capable of activating and expanding T cells, particularly CD4+ T cells, in the tumor draining lymph nodes, leading to increased trafficking of activated T cells into the TME." (PMID 39561007, 2024). "Taken together, high MAEL expression was identified as an independent indicator of poor benefits from ICI-based therapies over VEGFR/mTOR inhibitors in advanced ccRCCs, potentially mediated by tumor-infiltrating immune cells and the expression of PD-1 and CTLA-4 rather than PD-L1." (PMID 38301040, 2024). "Furthermore, treatment using a combination of anti-PDL1 and anti-CTLA4 did not improve tumor control." (PMID 39199612, 2024). "In addition, CTLA4 pathway can also significantly enhance the secretion of IL-2 by CD4+T cells and promote the proliferation, survival and tumor killer activity of T, NK and other immune cells in the tumor microenvironment." (PMID 38713378, 2024). "In general, patients with high TIDE scores are less likely to respond to immune checkpoint inhibitor (ICI) monotherapy (CTLA4 inhibitors or PD-1 inhibitors), and the predominance of high TIDE scores in the TNFSF9-high tumor suggests that ICI monotherapy may be less effective." (PMID 39000552, 2024).
tumor (continued). "Targeting PD-1, CTLA4, LAG3, or TIM3 axis may be a potential immunotherapy-based combination strategy to enhance population of cytotoxic effector T cells in patients with high level of Rab37+/PD-1+/TIM3+ tumor-infiltrating CD8+ T cells." (PMID 38321486, 2024). "MAPK directs interactions between tumor cells and the surrounding T-cell infiltrate, downregulates T-cell co-stimulatory molecules, and suppresses the expression of negative immune checkpoints such as PD-L1 and CTLA4 in several cancers." (PMID 39271499, 2024). "Anti–CTLA-4 treatment did not improve RT-induced TC-1 tumor control or OS." (PMID 38349740, 2024). "Thus, targeting combination therapy blocking VISTA, CTLA4, and PD1 could be a novel and attractive strategy for HGSOC treatment, considering the ambivalent role of VISTA in the HGSOC tumor cells." (PMID 38634058, 2024). "Moreover, STAT3 and CTLA4 exhibited upregulated profiles in Tregs of UTUC, which could hinder anti-tumor immunity, and suppress the production of immunosuppressive cytokines and metabolites, respectively." (PMID 38903524, 2024). "In this study, by using a computational biology tool (silico approach), we developed AYA22T-R2-13, a CTLA4/NKG2A dual receptor aptamer that blocks the inhibitory CTLA4/NKG2A receptors unleashing both T and NK cells and promotes NK and CD8+ T cell effector functions of tumor cell lysis." (PMID 38473398, 2024). "The results showed that the combination of cordycepin with CTLA-4 blockade significantly improved the efficacy and exhaustion state of infiltrating CD8+ T cells in the TME, reduced the number of Foxp3+ Tregs, and enhanced the anti-tumour immunity mediated by CD8+ T cells in the TME." (PMID 38953102, 2024). "Similarly, the CheckMate-142 trial reported that nivolumab, with or without ipilimumab (a CTLA-4 inhibitor), led to tumor reduction in a substantial proportion of patients." (PMID 38790167, 2024). "Furthermore, zero-valent iron nanoparticles (ZVI-NP), the ferroptosis inducer, induced cancer-specific cytotoxicity reducing the number of Tregs and decreasing the expression of PD-L1 on tumor cells and PD-1/CTLA4 on CD8+ T-cells, exerting an anti-tumor immune effect." (PMID 39359721, 2024). "Cytotoxic T-lymphocyte antigen 4 (CTLA-4), PD-1 and its ligand (PD-L1), and lymphocyte-activation gene 3 (LAG3) are expressed at higher levels in tumour-infiltrating lymphocytes, in the stroma and in the invasive front of MMRd tumours than in MMRp tumours (green panel)." (PMID 39271762, 2024). "In contrast to the use of vaccines as monotherapy, several studies have demonstrated their potential synergy in tumor control when used in combination with both standard therapies and immune checkpoint inhibitors such as Programmed Death-ligand 1 (PD-L1) and CTL Antigen 4 (CTLA-4)." (PMID 38400148, 2024). "In addition, after 1 week of treatment, combination of MRTX849 + anti–PD-1 with Treg-depleting anti–CTLA-4 therapy did not significantly affect tumor growth." (PMID 39485838, 2024). "PD1 expression is broader than CTLA4, as it can be found on T cells, B cells, NK cells, dendritic cells, macrophages, peripheral tissues, and also non-hematopoietic cells and non-lymphoid tissues (including tumor cells or stromal components of the TME)." (PMID 38611115, 2024). "During the later phase of tumor growth (days 11–14), CD44hiCD62loTcf1–CD8+ TILs in WT mice gradually gained expression of immune checkpoint molecules (PD-1, Tim3, Lag3, Ctla4) and TOX, a master transcription factor responsible for reprograming CD8+ T cells into the exhausted state." (PMID 38787791, 2024). "We found that in HNSCC, FAP expression is significantly correlated with CTLA4, HAVCR2, and CD276, suggesting that FAP may play a key role in regulating immune evasion and tumor immune suppression, but further exploration is needed to elucidate the specific mechanisms." (PMID 38826849, 2024).
tumor (continued). "CTLA-4 blockade with ipilimumab and other Abs has been reported to impede tumors through various mechanisms, primarily by favoring CD28 binding to CD80/86, especially in tumor-draining lymph nodes where APCs cross-present tumor antigens to activate tumor-reactive T-cells." (PMID 39684559, 2024). "Interestingly, IL7R− γδ TRM upregulates inhibitory molecules CTLA4 and PDCD1 in the TME more than IL7R+ γδ TRM, indicating that IL7R+ TRM may sustain longer life and provide a longer-lasting anti-tumor effect." (PMID 39454432, 2024). "DC-based vaccines induce the activity of CTLs expressing low levels of CTLA-4 and PD-1 to increase their cytolytic ability and to enhance the expression of different molecules (CXCR3 and CD103/CD49a) to empower the migration of CTLs towards the tumor microenvironment." (PMID 38255322, 2024). "More recently, a Reporting Recommendations for Tumor Marker Prognostic Studies (REMARK)-criteria blinded analysis of p-ERK established that this biomarker predicted OS from a trial in which recurrent GBM patients underwent administration of cavitary and systemic anti-CTLA-4 and anti-PD1 treatments." (PMID 39766048, 2024). "CCL14 expression has been found to correlate with the infiltration levels of various immune cells and the expression of immune checkpoint genes such as PD-L1 and CTLA-4, suggesting that CCL14 may exert its effects by modulating the tumor immune microenvironment." (PMID 39030403, 2024). "Concordantly, in a murine tumour model, concomitant stimulation of ICOS and blockade of CTLA-4 has proven to elicit potent synergistic anti-tumour responses, pleading for clinical exploration of combination regimen of ICOS stimulation with ICI, especially anti-CTLA-4 antibodies." (PMID 38440738, 2024). "Additionally, we analyzed the expression of CTLA‐4, PD‐1, LAG3, and TIGIT, which are inhibitory immune checkpoint molecules expressed in immune cells and exert inhibitory effects on the anti‐tumor functions of effector cells by binding to their respective ligands." (PMID 39659057, 2024). "CTLA-4 blockade increases the RT-induced Treg response and does not improve tumor control." (PMID 38349740, 2024). "However, it did not further increase tumor immunogenicity as no additional benefit in combination with anti-CTLA4 was detected." (PMID 39199612, 2024). "CTLA-4 absence or blockade may lower the threshold of TCR ligation required for T-cell activation, boosting T-cell stimulation in multiple ways and fostering more active tumor-reactive T-cells." (PMID 39684559, 2024). "In this study, we found that the CTLA4, CD68, and CD4 genes were closely related to THC and CMS1 CRC; therefore, this suggested that CHCs and THCs may act as a new marker of immunotherapies in tumor treatments in the future." (PMID 39499374, 2024). "Potential selection bias may influence our results, as patients with a higher tumor load might be more frequently selected for anti-CTLA-4/anti-PD-1 combination therapy rather than anti-PD-1 monotherapy." (PMID 39123384, 2024). "Given that CTLA-4, PD-1, and LAG-3 exert inhibitory effects on DCs and T cells via distinct mechanisms of action, it was hypothesized that simultaneously blocking multiple signals could potentially amplify the anti-tumor response." (PMID 38261139, 2024). "Notably, treatment with an IFN-g neutralizing Ab suppressed CD4+ cell, presumably CD4+ T cells, infiltration into tumors treated with the anti-CTLA-4 Ab, providing evidence that IFN-g produced from tumor-infiltrating Th1 can accelerate the infiltration of CD4+ T cells." (PMID 39106430, 2024). "Since the approval of anti-CTLA-4 for the treatment of metastatic melanoma in 2011, various T cell modulators, immune check point inhibitors (ICIs), CAR-T cells, TIL therapy, oncolytic viruses, and intra-tumor immune stimulators have emerged as promising therapeutics." (PMID 39104861, 2024).